FOXO3 (forkhead box O3)
Diseases named in the same sentence as FOXO3 in open-access papers (continued):
Sharing a sentence is not in itself a finding about the gene and the disease.
Hepatic steatosis (6 papers, 2018 to 2024). Steatosis is a term used to denote lipid accumulation within hepatocytes. "In particular, miR132 targets such as phosphatase and tensin homolog (Pten), Forkhead box O3 (FOXO3), and sirtuin 1 (Sirt1) are associated with hepatic steatosis, hyperlipidemia, and glucose regulation." (PMID 39596297, 2024). "For instance, PTEN, SIRT, FOXO3 were linked with hepatic steatosis, hyperlipidemia, and glucose regulation." (PMID 32962281, 2020). "To define the underlying mechanism by which FoxO3 functions in hepatic steatosis, we transfected siRNA into HepG2 cells for knockdown of FoxO3 and examined the mRNA levels of genes involved in hepatic TG metabolism." (PMID 31729980, 2019). "Mice that are deficient in hepatic FOXO3 are more susceptible to non-alcoholic steatohepatitis than WT controls, which provided strong evidence for FOXO3 protecting against the diet-induced fatty liver disease." (PMID 35222075, 2022). "Together, these data indicate that FoxO3 overexpression aggravates hepatic steatosis and reduces glucose tolerance and insulin sensitivity in mice fed a high-fat diet." (PMID 31729980, 2019). "FoxO3 gain-of-function caused hepatic TG deposition in C57BL/6 J mice on a chow diet and aggravated hepatic steatosis when fed a high-fat diet." (PMID 31729980, 2019). "To confirm the effect of FoxO3 gain-of-function on hepatic steatosis, we injected adenovirus into adult mice via the tail vein." (PMID 31729980, 2019). "Together, these data indicate that FoxO3 overexpression results in hepatic steatosis and impaired glucose tolerance." (PMID 31729980, 2019). "In this study, we confirmed the abnormally higher expression of FoxO3 in various steatosis cell models, animal models and patients with NAFLD, implying a close link between FoxO3 and fatty liver." (PMID 31729980, 2019). "Transgenic overexpression of a constitutively active FOXO3 decreases hepatic triglyceride level, indicating that FOXO3 could reverse hepatic steatosis." (PMID 35222075, 2022). "Thus, we identified that FoxO3 prompted hepatic steatosis via transcriptionally upregulating the expression of SREBP1c." (PMID 31729980, 2019). "Moreover, whether SREBP1c is required for the effect of FoxO3 on hepatic steatosis needs to be further explored." (PMID 31729980, 2019). "It is also upregulated in livers of NAFLD and mice models with NASH and hepatic steatosis while targeting SIRT1, PTEN, histone acetyltransferase P300 (P300), FOXO3, cytochrome P450 family 2 subfamily E member (CYP2E1)." (PMID 32962281, 2020). "Therefore, FOXO3 may have opposite regulatory effects on hepatic steatosis under insulin-dependent and non-independent signaling." (PMID 35222075, 2022).
Hypercholesterolemia (6 papers, 2016 to 2024). An increased concentration of cholesterol in the blood. "Inactivation of FOXO1 and FOXO3 also results in hypertriglyceridemia and hypercholesterolemia due to increased hepatic lipid secretion and mild steatosis, indicating that FOXO1 and FOXO3 work together to inhibit critical pathways in adipogenesis as well as enhance gluconeogenic genes." (PMID 39618816, 2024). "Examples of such master regulators are FOXO3, which controls mechanisms linked to MPN, RA, hypercholesterolemia, and hypertriglyceridemia, and PRKCG that controls canonical pathways related to regulation of blood pressure, platelet count, and function and linked to RA." (PMID 34580418, 2021).
hyperlipidemia (6 papers, 2014 to 2024). "In this study, we investigated the association between hyperlipidemia, intimal injury, the expression of NAD-dependent deacetylase sirtuin-3 (SIRT-3), FOXO3, and oxidative stress." (PMID 38333571, 2024). "The hepatic suppression of FOXO1 and FOXO3 causes hypoglycemia and hyperlipidemia in FOXO1 and FOXO3 knockout mice; moreover, the expression of hepatic FOXOs affects the reduction of gluconeogenic gene expression and insulin resistance." (PMID 35256743, 2022). "The results of early network pharmacology suggested that the PI3K/AKT pathway and its downstream FOXO3 and ERα proteins were related to the improvement of hyperlipidemia by PCE." (PMID 34925692, 2021). "This study was designed to investigate the association between hyperlipidemia, intimal injury, chronic inflammation, and the expression of NAD-dependent deacetylase SIRT-3, FOXO3, antioxidant genes, and oxidative stress in carotid arteries of hypercholesterolemic Yucatan microswine." (PMID 38333571, 2024).
kidney cancer (6 papers, 2018 to 2025). Primary or metastatic malignant neoplasm involving the kidney. "In kidney cancer cells, it has been shown that vitamin D3 promotes apoptosis by activating forkhead box O3 (FOXO3) through downregulation of phosphorylated serine-threonine protein kinase Akt and extracellular signal-regulated kinase (Erk)." (PMID 29849001, 2018). "In addition, there is strong evidence that the FOXO3 is involved in the metastasis of multiple cancers, including breast, pancreatic, and kidney cancers." (PMID 36555288, 2022). "In the A-498 kidney cancer cell, a positive correlation (p < 0.05) was observed between miR-181a expression and the mRNA expression of FOXO1, FOXO3, PDCD4, AKT3, JNK1 and LAMTOR3." (PMID 41462911, 2025). "It was further shown that HJURP induces apoptosis in kidney cancer cells by promoting ROS accumulation through inactivation of PPARγ/SIRT1 and downstream Forkhead box O3 (FOXO3a) signaling." (PMID 37025176, 2023).
papillary thyroid carcinoma (6 papers, 2011 to 2026). "FoxO3 transactivation is effectively inhibited by RET/PTC (rearranged in transformation/papillary thyroid carcinomas) kinase, the gene rearrangement of which is the most common rearrangement in papillary thyroid cancer." (PMID 21249150, 2011). "In papillary thyroid carcinoma, SNHG5 binds and stabilizes RBM47, preventing ubiquitin-mediated degradation of FOXO3 via recruitment of USP21." (PMID 41550840, 2026).
steatosis (6 papers, 2014 to 2024). Increased lipid within the cytoplasm of cells. "Consistent with our findings, FoxO3 knockout mice fed the Lieber-DeCarli alcohol diet for 3 weeks developed more severe steatosis, inflammation and liver injury compared to wild type mice likely due to decreased expression of MnSOD, another target gene of FoxO3a that attenuates oxidative stress." (PMID 25536043, 2014). "Moreover, we found that FoxO3 KO mice had decreased expression of Atg genes and had increased steatosis and liver injury compared to wild type mice after acute ethanol treatment." (PMID 25140315, 2014). "As a result, we reasoned that steatosis increased the generation of ROS in hepatocytes, changed the expression of the AMPK/FOXO3/TXNIP signaling cascade, created an imbalance between pro-oxidants and antioxidants, and resulted in oxidative stress." (PMID 36144229, 2022).
cholangiocarcinoma (5 papers, 2018 to 2025). A carcinoma that arises from the intrahepatic biliary tree (intrahepatic cholangiocarcinoma) or from the junction, or adjacent to the junction, of the right and left hepatic ducts (hilar cholangiocarcinoma). "The effects of FOXOs on cellular ROS levels are debatable, with one study having showed that FOXO3 knockdown led to decreased ROS levels in cholangiocarcinoma cells, which also protected cells from oxidative-stress-induced cell death." (PMID 35883815, 2022). "Nevertheless, exogenous H2O2 treatment was found to activate FOXO3, while a separate study showed that FOXO3 depletion sensitized cholangiocarcinoma cells to H2O2-induced damage, demonstrating its role in controlling adaptation to oxidative stress." (PMID 35883815, 2022).
colitis (5 papers, 2015 to 2025). Inflammation of the colon. "For instance, the activation of the M2-type macrophage/Foxo3 axis has been shown to alleviate the colonic inflammatory response and improve intestinal mucosal barrier function in mice with dextran sulfate sodium (DSS)-induced colitis." (PMID 41030455, 2025).
dementia (5 papers, 2021 to 2026). Loss of intellectual abilities interfering with an individual's social and occupational functions. "To date, we have ruled out cancer, but not a genotypic effect of FOXO3 on stoke and dementia." (PMID 37561089, 2023).
esophageal cancer (5 papers, 2014 to 2021). A primary or metastatic malignant neoplasm involving the esophagus. "Our IHC analysis also indicated FOXO3 levels were lower in esophageal cancer tissues than in normal esophageal tissues." (PMID 30514328, 2018). "Collectively, our findings suggested upregulated expression of miR-10b-3p caused by promoter hypomethylation contributed to the progression of ESCC and miR-10b-3p suppresses tumor initiation and progression of esophageal cancer by regulating FOXO3." (PMID 30514328, 2018). "Because of intraepithelial neoplasia importance in tumorigenesis of esophageal cancer, occurrence of autophagy and expression of FOXO3, MYD88, and GAPDH genes should be studied in this stage." (PMID 24527027, 2014). "The upregulation of FOXO3, GAPDH, and MYD88 variants in esophageal cancer suggests a role for autophagy and provides new insight into the biology of esophageal cancer." (PMID 24527027, 2014). "Because this is the first report of the overexpression of the FOXO3, GAPDH, and MYD88 genes in esophageal cancer cells, the precise role of these genes in esophageal cancer remains to be elucidated." (PMID 24527027, 2014). "Furthermore, a survival plot showed that the high expression of some hub genes (FOXO3, CCR5, PECAM1, ESR1, and SMAD2) was associated with high risk of death in patients with esophageal carcinoma and other squamous cell carcinomas." (PMID 33747034, 2021). "Our results indicated that FOXO3 was upregulated 5.187-fold in esophageal cancer tissues." (PMID 24527027, 2014). "The work presented here identified the FOXO3 gene as being overexpressed in esophageal cancer." (PMID 24527027, 2014). "In light of its transcriptional activity and regulatory effects on the process of autophagy in skeletal muscle, FOXO3 could increase the expression level of autophagy-related genes in esophageal cancer tissues." (PMID 24527027, 2014). "We propose that FOXO3, GAPDH, and MYD88 are novel targets for combating autophagy in esophageal cancer." (PMID 24527027, 2014). "In conclusion, using the SSH method, our study revealed for the first time that the FOXO3, MYD88, and GAPDH genes are overexpressed in esophageal cancer." (PMID 24527027, 2014). "In this study, suppression subtractive hybridization was used to identify the overexpressed genes, FOXO3, MYD88, and GAPDH, which have potential roles in the induction of autophagy in esophageal cancer cells." (PMID 24527027, 2014). "Considering the fundamental role of autophagy in tumorigenesis and the high expression levels of FOXO3, MYD88 and GAPDH in esophageal cancer, further studies are needed to evaluate the roles of these genes and autophagy in the development of esophageal cancer." (PMID 24527027, 2014). "The overexpression of the FOXO3, MYD88, and GAPDH genes could lead to the induction of autophagy genes in esophageal cancer." (PMID 24527027, 2014).
gastric adenocarcinoma (5 papers, 2013 to 2024). "FOXO3 inhibits human gastric adenocarcinoma cell growth by promoting autophagy in an acidic microenvironment." (PMID 37990103, 2023). "Moreover, FOXO3 downregulation in ESCC patients accounted for lymph node metastasis, and its low expression correlated with a larger tumor size in gastric adenocarcinoma." (PMID 34771514, 2021).
liver diseases (5 papers, 2017 to 2022). "Forkhead box O3 (FOXO3), an essential transcription factor related to liver disease, has been linked to cancer progression." (PMID 34771514, 2021). "Although FOXO3 is ubiquitously expressed, hepatocytes usually exhibit high levels, and this transcription factor seems to be implicated in the pathogenesis of liver disease." (PMID 34771514, 2021). "FOXO3 is not only a direct transcriptional regulator for gluconeogenesis but is also required for cellular antioxidant defense in liver diseases." (PMID 35222075, 2022). "Previous studies have proposed that the transcription factor FoxO3 is involved in various liver diseases, but its exact role in the regulation of liver regeneration remains largely unclear." (PMID 35750775, 2022). "Clinically, we suggest analyzing FOXO3 activation status in patients with liver diseases, in addition to PI3K/Akt signaling." (PMID 31488102, 2019). "FOXO3 is required for antioxidant responses and autophagy, its expression alters in liver diseases." (PMID 29137289, 2017).
acne (4 papers, 2017 to 2023). An inflammatory process of the sebaceous glands which is characterized by comedones, nodules, papules and/or pustules on the skin. "Among many regulatory effectors, AKT phosphorylates and thereby inactivates the transcription factors FoxO1 and FoxO3, which are predicted to play a key role in the pathogenesis of acne." (PMID 37998335, 2023).
B Cell Lymphoma (4 papers, 2016 to 2025). "As Eμ-myc and FoxO3−/−Eμ-myc mice develop pre-B or B-cell lymphomas, the impact of FoxO3 loss on B lymphopoiesis was of particular interest." (PMID 26764572, 2016).
brain injury (4 papers, 2019 to 2026). Acute and chronic (see also brain INJURIES, CHRONIC) injuries to the brain, including the cerebral hemispheres, CEREBELLUM, and brain STEM. "It has been reported that the overexpression of miR-27a downregulates autophagy in neurons and inhibits neurodegeneration by targeting FOXO3a (Forkhead bOX O3a, a transcription factor that promotes autophagy) in mouse neurons after a traumatic brain injury." (PMID 35204010, 2022).
cognitive decline (4 papers, 2020 to 2023). "Especially, the observed and persistent neuronal changes such as cerebral ROS formation, downregulation of nNOS and FOXO3 is worrisome as these adverse processes are also features of neurodegeneration and cognitive decline." (PMID 35174211, 2021).
endometrial carcinoma (4 papers, 2017 to 2024). A malignant tumor arising from the epithelium that lines the cavity of the uterine body. "The complex interplay between Sirtuin 1 (SIRT1) and FOXO3 in endometrial cancer (EC) remains understudied." (PMID 39266959, 2024).
female infertility (4 papers, 2015 to 2023). Diminished or absent ability of a female to achieve conception. "Transgenic mouse models with constitutively active FoxO3 demonstrate that the overexpression of FoxO3a impaired oocyte growth and folliculogenesis, leading to female infertility." (PMID 36297035, 2022). "Interestingly, Foxo3 knockout in mice results in early depletion of functional ovarian follicles and in female sterility, indicating that FOXO3 plays a specific role in epithelial cells of the ovary." (PMID 28778953, 2017). "Mice lacking FOXO3 manifest age-related female infertility, whereas targeted disruption of FOXO1 leads to midgestational death, attributed to abnormal vascular/cardiovascular morphogenesis." (PMID 37835658, 2023).
fibrosis (4 papers, 2021 to 2025). the formation of excess fibrous connective tissue in an organ or tissue in a reparative or reactive process. "Furthermore, Foxo3 effectively prevented cardiac fibrosis, alleviated lipid metabolic dysfunction, and normalized the expression of genes involved in the lipid metabolism pathway." (PMID 41237237, 2025).
intervertebral disc degeneration (4 papers, 2018 to 2025). "Similarly, MSC-derived exosomes effectively reduced NLRP3 inflammasome to ameliorate intervertebral disc degeneration and protected against hypoxia/reoxygenation-induced pyroptosis of cardiomyocytes through the miRNA-100-5P/FOXO3/NLRP3 pathway." (PMID 34294138, 2021). "Given the role of FOXO3 in the circFGFBP1 expression, we finally demonstrated that FOXO3-activated circFGFBP1 inhibits ECM degradation and NP cell death via the miR-9-5p/BMP2 axis in intervertebral disc degeneration in vivo and in vitro." (PMID 36986573, 2023).
mantle cell lymphoma (4 papers, 2014 to 2023). Mantle cell lymphoma is a rare form of malignant non-Hodgkin lymphoma affecting B lymphocytes in the lymph nodes in a region called the ``mantle zone''. "For example, in mantle cell lymphoma (MCL), PI3K and AKT, but not mammalian target of rapamycin (mTOR), inhibitors have been demonstrated to be able to cause significant reduction in leukaemic cell viability, which is again associated with FOXO3 nuclear translocation and activation." (PMID 29180117, 2018).
myeloid leukemia (4 papers, 2016 to 2025). A clonal proliferation of myeloid cells and their precursors in the bone marrow, peripheral blood, and spleen. "We further show that FOXO1, but not its close paralog FOXO3, can reprogram myeloid leukemia cells and induce B-lineage gene expression." (PMID 36282572, 2022).
myeloproliferative disease (4 papers, 2015 to 2019). "Loss of FOXO3 in mice has previously been shown to result in a myeloproliferative disease." (PMID 25969990, 2015). "Further studies demonstrated that Foxo3-/- mice have a mild myeloproliferative disease with splenic neutrophilia, an increased frequency of at least one type of myeloid progenitor cell, and enhanced extramedullary hematopoiesis." (PMID 25969990, 2015). "In addition, they showed that JAK2V617F-positive erythroblasts derived from myeloproliferative neoplasm patients also displayed the increased ROS level and reduced nuclear FOXO3 compared with the control erythroblasts." (PMID 31540495, 2019). "This analysis focused on genes (Srpk2, Hes1, Mtor, Pdp1, Meis1, Gfi1, Foxo3, Stra13, Hif1α, and Cebpε) involved in HSC proliferation; maintenance of quiescence, growth, and stem cell exhaustion; and development of myeloproliferative disorder in young and geriatric mice." (PMID 27366154, 2016).